GIMAP7 (GTPase, IMAP family member 7)
Description:
The dimer has GTPase activity; the active site contains residues from both subunits.
Synonyms: IAN7; MGC27027; hIAN7
Tractability: Small molecule: a structure with a bound ligand is known. PROTAC: ubiquitination databases record sites on it; its protein half-life has been measured.
Gene: Protein-coding gene on chromosome 7 (150,514,872 to 150,521,073, forward strand). Ensembl gene ENSG00000179144.
Subcellular location: Lipid droplet; Cytoplasm; Endoplasmic reticulum; Golgi apparatus
Subcellular location (Human Protein Atlas): Golgi apparatus; Vesicles
Gene Ontology:
Molecular function: GTP binding; GTPase activity; identical protein binding; protein binding; protein homodimerization activity
Biological process: GTP metabolic process
Cellular component: endoplasmic reticulum; Golgi apparatus; lipid droplet; cytoplasm
Genetic constraint (gnomAD): Missense variants: 268 observed, 303.36 expected, observed/expected ratio (o/e) 0.88, 90% interval 0.8 to 0.98. Synonymous variants: 116 observed, 112.27 expected, observed/expected ratio (o/e) 1.03, 90% interval 0.89 to 1.21.
Homologues: Orthologues: chimpanzee GIMAP7 (99% identical), dog GIMAP7 (72% identical), macaque GIMAP7 (66% identical), mouse Gimap7 (60% identical), rat Gimap7 (58% identical). Paralogues in human: GIMAP4 (37% identical), GIMAP5 (34% identical), GIMAP1 (32% identical), GIMAP2 (30% identical), GIMAP6 (30% identical), GIMAP8 (29% identical), GIMD1 (17% identical).
Diseases named in the same sentence as GIMAP7 in open-access papers:
GIMAP7 is named in the same sentence as 21 diseases in open-access papers, as found by Europe PMC text mining. Sharing a sentence is not in itself a finding about the gene and the disease. The quoted sentences say what the papers report.
breast carcinoma (3 papers, 2020 to 2025). "The transcriptional levels of GZMB, LCP2, and SELL were significantly upregulated, whereas GIMAP7 was significantly downregulated, in breast cancer compared with normal breast tissue." (PMID 33042828, 2020). "Another bioinformatic analysis on GIMAP family members indicated that GIMAP7 together with GIMAP1, GIMAP5, GIMAP6, and GIMAP8, are lowly expressed in breast cancer tissues." (PMID 38151913, 2024). "Bioinformatics show GIMAP1, GIMAP5, GIMAP6, GIMAP7, and GIMAP8 are downregulated in breast cancer." (PMID 40535419, 2025).
lung carcinoma (3 papers, 2021 to 2025). "Similarly, GIMAP7, a member of the GTPase family, is associated with regulating immune cell infiltration and the development and progression of multiple cancers, including lung cancer." (PMID 40270498, 2025). "The survival analysis of the GIMAP family was performed, and the results showed that high levels of GIMAP1, GIMAP2, GIMAP4, GIMAP5, GIMAP, GIMAP7 and GIMAP8 mRNA expression levels were associated with better overall survival of patients with lung cancer." (PMID 34604035, 2021). "Among them, GIMAP7 was the most significantly downregulated in lung cancer, CX3CR1 was the most upregulated and MYLIP was the most downregulated in systemic sclerosis." (PMID 33691643, 2021).
COVID-19 (2 papers, 2022 to 2023). A disease caused by infection with severe acute respiratory syndrome coronavirus 2. "We constructed a 3-gene signature consisting of ARG1, GIMAP7, and RFX2 models for the assessment of COVID-19 severity and prognosis, and found that they are associated with neutrophils, T cells, and hematopoietic stem cells, respectively." (PMID 36352845, 2022). "Therefore, targeting GIMAP7 may reduce the extent of COVID-19 and AF by maintaining the number of lymphocytes." (PMID 36352845, 2022). "To further explore the functional and clinical value of ARG1, GIMAP7, and RFX2, we analyzed the Bonn cohort, which included peripheral blood scRNA-seq data from 19 control and 22 COVID-19 patients." (PMID 36352845, 2022). "We constructed a 3-gene signature consisting of ARG1, GIMAP7, and RFX2 for the assessment of COVID-19 severity and prognosis, and determined the cell-specific expression of these genes." (PMID 36352845, 2022). "A LASSO regression classification model composed of ARG1, GIMAP7, and RFX2 was constructed, which could be used to distinguish the severity of COVID-19." (PMID 36352845, 2022).
lung adenocarcinoma (2 papers, 2024 to 2025). A carcinoma that arises from the lung and is characterized by the presence of malignant glandular epithelial cells. "Our objective was to explore the function of GIMAP7 in the progression of lung adenocarcinoma (LUAD)." (PMID 38151913, 2024). "High expression of GIMAP7 represses the Smo/AMPK signaling pathway in lung adenocarcinoma cells." (PMID 38151913, 2024).
pancreatic adenocarcinoma (2 papers, 2020 to 2023). "GIMAP7 was associated with the infiltration levels of immunocytes, and the inhibition of GIMAP7 would down-regulated the level of FOXO1 expression in pancreatic adenocarcinoma." (PMID 33115964, 2020). "GIMAP7 also has a positive correlation with CD8+ T cell infiltration in pancreatic adenocarcinoma." (PMID 37895181, 2023).
Allergy (1 paper, 2019). An allergy is an immune response or reaction to substances that are usually not harmful. "The up-regulated genes have been previously associated with asthma; hyper-reactivity and allergy (CCR2, HRH2, PTEN); lung development and apoptosis (CHRNA7, RTKN2); and immune function (GIMAP4, GIMAP7, KLRC3 and CD99)." (PMID 30971730, 2019).
anaplastic large cell lymphoma (1 paper, 2021). Anaplastic large cell lymphoma (ALCL) is a rare and aggressive peripheral T-cell non-Hodgkin lymphoma, belonging to the group of CD30-positive lymphoproliferative disorders, which affects lymph nodes and extranodal sites. "The expression of GIMAP5 occurs in many T cell leukemic cell lines and in anaplastic large cell lymphoma (ALCL) cell lines while the expression of GIMAP1, GIMAP2, GIMAP6 and GIMAP7 were down-regulated in ALCLs." (PMID 34135906, 2021).
Cognitive impairment (1 paper, 2024). Abnormal cognition is characterized by deficits in thinking, reasoning, or remembering. "Genes involved in the cognitive impairment MAG, GDF15, GPR176, and EPHB1 (upregulated), BCL11B, GIMAP7, and ACOD1 (downregulated) were differentially expressed." (PMID 38755198, 2024).
Immunodeficiency (1 paper, 2021). Failure of the immune system to protect the body adequately from infection, due to the absence or insufficiency of some component process or substance. "A region on Chr4 included three GTPase genes (GIMAP7, GIMAP4, and GIMAP8), IMAP family members that have been related to the primary immunodeficiency pathway and were shown to play a major role in feed utilization and the metabolism of lipids, sugars, and proteins in Jersey cattle." (PMID 33633776, 2021).
lymphopenia (1 paper, 2009). Reduction in the number of lymphocytes. "While we can exclude theinvolvement of the members of the Gimap family proximal to D4Rhw6 (Gimap8, Gimap9, Gimap4, Gimap6, and Gimap7)in the development of lymphopenia, we cannot exclude that they may play a rolein the development of T1D." (PMID 19421422, 2009).
melanoma (1 paper, 2023). A malignant, usually aggressive tumor composed of atypical, neoplastic melanocytes. "Of note, GIMAP7 mRNA expression displays impressive correlations with immune checkpoints PDL2, CD96, TIGIT, BTLA, other immune checkpoints in melanoma, and across 30 cancer types." (PMID 36588164, 2023). "CYTH4, DENND1C, AOAH, TBC1D10C, EPSTI1, GIMAP7, and FASL (FAS ligand) were novel predictors of ICB therapy and displayed high level of correlations with multiple immune checkpoints in melanoma and across 30 human cancers." (PMID 36588164, 2023). "In addition to melanoma, CYTH4, AOAH, DENND1C, TBC1D10C, EPSTI1, SERPINB8, and GIMAP7 stratify responders and non-responders to ICB in other cancer types." (PMID 36588164, 2023).
oral cancer (1 paper, 2021). "Another report showed that downregulation of GIMAP7 at both protein and mRNA levels observed in serum and tissue samples of oral cancer patients may imply that GIMAP7 has an anticancer effect." (PMID 33691643, 2021).
oral squamous cell carcinoma (1 paper, 2024). "In addition, GIMAP7 has been recognized as a putative biomarker in oral squamous cell carcinoma as its expression has been found to be significantly low in the serum of patients with oral squamous cell carcinoma compared with healthy controls." (PMID 38151913, 2024).
systemic sclerosis (1 paper, 2021). A chronic disorder, possibly autoimmune, marked by excessive production of collagen which results in hardening and thickening of body tissues. "Downregulation of GIMAP gene may regulate immune cell viability or development affecting cancer progression, however, high expression of GIMAP7 in systemic sclerosis has not been reported, which needs further exploration." (PMID 33691643, 2021).
cancer (10 papers, 2020 to 2025). A tumor composed of atypical neoplastic, often pleomorphic cells that invade other tissues. "GTPase immunity‐associated protein 7 (GIMAP7) has been previously recognized as a prognostic marker in pan‐cancer." (PMID 38151913, 2024). "Analysis of GIMAP7 in pan-cancers has shown that GIMAP7 is significantly downregulated in most cancers and its expression is associated with the development and progression of many cancers." (PMID 36581994, 2022). "GIMAP7 was reported as a pan-cancer biomarker, showing a positive correlation to T cell infiltration of tumors, PD-L1 expression, microsatellite instability, TMB score, and TIDE score." (PMID 40989699, 2025). "Our data further confirmed the potential of GIMAP7 for use as a cancer prognostic marker in the clinical setting." (PMID 38151913, 2024). "In the time since GIMAP7 was initially identified, it has subsequently been shown to be a potential marker for various cancer types, which further supports its immune-related role." (PMID 36785619, 2023). "CYTH4, AOAH, DENND1C, TBC1D10C, EPSTI1, SERPINB8, and GIMAP7 are novel and robust individual genes in predicting resistance to ICB in multiple cancer types." (PMID 36588164, 2023). "Results: 239 genes were identified for further survival analysis, 5 of which were overlapping genes across at least five cancer types, including RHEBL1, PDE4B, ANKRD55, EPHB2, and GIMAP7." (PMID 34262492, 2021). "GIMAP7 belongs to the GTP-binding superfamily and the prognostic role of GIMAP7 in cancer has not been explored yet." (PMID 33042828, 2020). "In addition to transcription factors, in AML samples, we identified the upregulation of genes that were reported to accelerate leukaemogenesis, including S100A8, S100A9, and RPS26, and the downregulation of genes related to cancer control and defence, such as XIST, GIMAP7, NKG7, and GNLY." (PMID 37615858, 2024).
tumor (8 papers, 2020 to 2025). "A xenograft tumor model was established in nude mice to evaluate the effects of GIMAP7 on tumor growth." (PMID 38151913, 2024). "GIMAP7 is considered to participate in the progression of many types of tumor, and its expression is downregulated in most malignancies." (PMID 38151913, 2024). "GIMAP7 overexpression notably reduced the tumor weight and volume." (PMID 38151913, 2024). "In addition, we also confirmed that GIMAP7 could inhibit xenograft tumor growth by suppressing Smo/AMPK signaling in vivo." (PMID 38151913, 2024). "Furthermore, the role of GIMAP7 in inhibiting tumor growth was verified in vivo." (PMID 38151913, 2024). "We also used data from Human Protein Profiles to demonstrate that the proteins encoded by seven immune-related genes were expressed at different degrees in HCC tissues, among which TMC8, BIN2, GIMAP7, and SPOCK2 were strongly to moderately positive in tumours." (PMID 32213661, 2020). "Similarly, the expression of BTN3A1, CSF2RB, GIMAP7, GZMB, HCLS1, LCP2, and SELL was positively correlated with the infiltration of B cells, CD8+ T cells, CD4+ T cells, neutrophil, and DCs, but was negatively correlated with the tumor purity." (PMID 33042828, 2020). "Interestingly, our data show a significant decrease in mRNA levels of GIMAP4, GIMAP6, GIMAP7 and GIMAP8 in BC tissues, compared to DCIS tissues, and non-tumor breast tissues from either women with or without BC (supplementary 2)." (PMID 32523132, 2020).
infection (3 papers, 2023 to 2025). The state of being infected such as from the introduction of a foreign agent such as serum, vaccine, antigenic substance or organism. "For example, GIMAP7 was consistently down- and BCL6 transcription repressor (BCL6) upregulated from 4 h to 7 days post-infection (and the present study), regardless of the cellular proliferative response to the TCR stimulus." (PMID 37111397, 2023).
GIMAP7 also shares sentences with these, for which no sentence is quoted: asthma (1 paper); lung squamous cell carcinomas (1); polycystic ovary syndrome (1); Stroke (1).